RNU6-234P (RNA, U6 small nuclear 234, pseudogene)
Gene: Small nuclear RNA gene on chromosome 2 (238,412,642 to 238,412,745, forward strand). Ensembl gene ENSG00000202099.
Homologues: Orthologues: chimpanzee U6 (97% identical), macaque U6 (91% identical), pig U6 (72% identical), pig U6 (66% identical), dog U6 (62% identical), rat LOC120100188 (62% identical), mouse Gm22764 (61% identical), pig U6 (61% identical). Paralogues in human: RNU6-1181P (81% identical), RNU6-106P (80% identical), RNU6-16P (80% identical), RNU6-181P (80% identical), RNU6-633P (80% identical), RNU6-10P (79% identical), RNU6-116P (79% identical), RNU6-1209P (79% identical), RNU6-1251P (79% identical), RNU6-45P (79% identical), RNU6-744P (79% identical), RNU6-921P (79% identical), and 1283 more.